MTOR (mechanistic target of rapamycin kinase)
Diseases named in the same sentence as MTOR in open-access papers (continued):
Sharing a sentence is not in itself a finding about the gene and the disease.
breast cancer (continued). "The mTOR inhibitor everolimus has been approved and frequently utilized in combination with the aromatase inhibitor exemestane in patients with HR+ progressed breast cancer after nonsteroidal aromatase inhibitor therapy." (PMID 37190133, 2023). "One study reported that α-hederin inhibits growth and induces apoptosis in breast cancer cells, while another mentioned that α-hederin induces autophagy and cell death in colorectal cancer cells via an ROS-dependent mechanism in breast cancer cells and AMPK/mTOR signaling pathway activation." (PMID 36986504, 2023). "Different hypotheses such as the activation of cell growth signaling pathways like the PIK3A/Akt/mTOR pathway, the overexpression of EGFR or the activation of the RAS-MEK-MAPK pathway have been the subject of research in breast cancer and have led to the development of specific treatments." (PMID 37924026, 2023). "The interactions of the mTOR cascade with STAT-mediated signaling (e.g., in immunity), and the roles attributed to STAT3 and STAT1 in promoting PD-L1 expression, have led us to inquire in depth about the potential involvement of STAT3 and STAT1 in PD-L1-mediated effects in breast cancer cells." (PMID 37830552, 2023). "Combined with basal breast cancer markers CK 6 and Vimentin, the MAPK-signaling protein Erk1/2- pThr202/Tyr204 and the active mTOR signaling protein eIF4E-pSer209, these proteins could differentiate PAB resistant from PAB sensitive BC-PDMs (Mann Whitney U-test, ***p < 0.001)." (PMID 37596623, 2023). "UA has demonstrated its anti-cancer effect in several cancer types including breast cancer, colorectal cancer, ovarian cancer, lung cancer, and prostate cancer by targeting multiple signaling pathways such as MAPK, NF-κB, JAK/STAT, PI3K/Akt/mTOR, and Wnt/β-catenin." (PMID 37376594, 2023). "Thus, immunoblotting of multiple mTORC1 core proteins and its downstream targets (mTOR, Raptor, p70S6K, rpS6 and 4E-BP1) revealed that the mTORC1 pathway is inhibited in matrix-deprived breast cancer cells which is suggestive of inhibition of global protein translation under matrix-detached stress." (PMID 37425300, 2023). "In addition, the treatment-induced breast cancer cell apoptosis and autophagy, activated the c-Jun N-terminal kinase (JNK) signaling pathway, suppressed the protein kinase B (AKT)/mammalian target of rapamycin (mTOR) signaling pathway, and down-regulated IAP and Bcl-2 family protein expression." (PMID 34282830, 2022). "Accompanied with cell invasion data as well as the deregulation of AKT, mTOR and HER2, which play an important role in carcinogenesis, we suggest that the combination therapy of TZ and BMS-202 may serve as an inhibitor of HER2+ breast cancer cell invasion." (PMID 36568154, 2022). "Indeed, breast cancer cells not expressing functional BRCA1 have been shown to be more responsive towards mTOR antagonists." (PMID 36428613, 2022). "Given the phosphorylation of ER, the dynamic activation of the ER membrane complex and the role of mTOR in AMPK and insulin signalling described earlier this phosphorylation site may present a key step in the cellular response to progesterone in breast cancer." (PMID 36034422, 2022). "Because the synergistic effects might be due to a direct link of METAPs to PI3K signaling, we analyzed the activity of the PI3K pathway by means of the phosphorylation status of three players (Akt, mTOR, S6) upon METAP1 or METAP2 knockdown in human breast cancer cells." (PMID 35673573, 2022). "The levels of p-AKT/AKT and p-mTOR/mTOR of si-LINC00665 group declined significantly compared with si-con group in MCF7 and MDA-MB-231 cells (P < 0.01), suggesting that LINC00665-siRNA inhibited the survival of breast cancer cells through inactivating the AKT/mTOR signaling pathway." (PMID 35152838, 2022).
breast cancer (continued). "We speculate that under SCA treatment, the PI3K–Akt–mTOR pathway was inhibited in breast cancer cells, and that the low activity of mTOR was not enough to exert an inhibitory effect on autophagy so that the autophagic process could be activated." (PMID 36408240, 2022). "However, to our knowledge, this study is the first to demonstrate that exposure of epithelial breast cancer cells to medium collected from contracting skeletal muscles results in a rescue of DEPTOR within the cancer cell, blunting mTOR signaling and with consequent reductions in protein synthesis." (PMID 36388131, 2022). "Importantly, PI3K/AKT/mTOR is critical to maintaining the CSC population in various cancers, including nasopharyngeal carcinoma, glioma, pancreatic cancer, lung cancer, prostate, and breast cancer." (PMID 36226253, 2022). "Functional pathway analysis revealed enrichment of several gene pathways in WTC-exposed breast cancer cases including endocytosis, proteoglycans in cancer, regulation of actin cytoskeleton, axon guidance, focal adhesion, calcium signaling, cGMP-PKG signaling, mTOR, Hippo, and oxytocin signaling." (PMID 35564499, 2022). "For instance, a decrease in PI3K/AKT/mTOR system activity by CTDs blocks the activation of crucial oncogenic molecules, i.e., MYC, which are inhibited in almost 50% of human cancers, including head and neck cancer, small-cell lung cancer, neuroblastoma, and breast cancer." (PMID 35276890, 2022). "The mTOR inhibitors temsirolimus and everolimus were the first to enter clinical practice in the treatment of advanced renal cell cancer, with indications later expanding to include ER+ HER2-negative (HER2−) breast cancer, pancreatic neuroendocrine tumors, and astrocytomas." (PMID 36046843, 2022). "Similarly, prospective clinical trials also confirmed that the CDK4/6 inhibitor, palbociclib, the mTOR inhibitor, everolimus, and the PI3K inhibitor, buparlisib may improve progression-free survival (PFS) in patients with advanced breast cancer." (PMID 35317849, 2022). "Upregulation of human epidermal growth factor receptor 2 (HER2) in breast cancer cells enhances the expression of fatty acid synthesis genes such as ACC1 and FASN, which are suppressed by PI3K and mTOR inhibitors, indicating that PI3K/AKT/mTOR can regulate fatty acid synthesis." (PMID 35624775, 2022). "MK-2206 is an inhibitor of Akt in the PI3K/Akt/mTOR pathway, and a multicenter phase II clinical study has demonstrated that its combination with neoadjuvant therapy can improve the pathological complete response (pCR) rate of HR-negative and HER2-positive breast cancer." (PMID 36414988, 2022). "Indeed, studies have shown that BPA could promote cell proliferation by binding to the GPER in breast cancer cells, which activates the phosphoinositide 3-kinase (PI3K)/protein kinase B (Akt)/mammalian target of rapamycin (mTOR) signalling pathway." (PMID 36011004, 2022). "The individual expression of the constitutively active mutants, Myc-tagged CDC42 (Myc-CDC42(F28L)), Myc-CDC42b(F28L), or the carboxyl terminally V5-tagged ACK (ACK-V5) did not affect the expression of either mTOR or the EGFR in MDA-MB-231 breast cancer cells (lanes 1–4, columns 1–4)." (PMID 36206843, 2022). "Based on these data, we hypothesize that ASS1 expression restores arginine metabolism in M231-ADIR cells, whereas TREM1 expression stimulates AKT/mTOR/STAT3 and a CCL2 feed-forward loop to provide survival signals contributing to ADI resistance in breast cancer cells." (PMID 33664852, 2021).
breast cancer (continued). "Thus, to uncover new chemotherapeutic strategies for cats, the antiproliferative effects of two TKi (lapatinib and neratinib), and their combination with a mTOR inhibitor (rapamycin), were evaluated in FMC cell lines (CAT-M, FMCp and FMCm) and compared with a human breast cancer cell line (SkBR-3)." (PMID 33800900, 2021). "Besides an inhibitory effect on proliferation, migration, and invasion of breast cancer cells, the PI3K/mTOR-inhibitor PKI-402 was also shown to inhibit RANKL-mediated osteoclastogenesis and, thus, tumor-induced osteolysis through suppression of the PI3K/AKT/mTOR pathway." (PMID 34064589, 2021). "The PI3K/AKT/mTOR signaling cascade is involved in escape pathways from hormonal therapy (HT) in breast cancer and may be independent of ER activation." (PMID 34445095, 2021). "The expression of XCR1 is inhibited in human breast cancer cells in vitro and in vivo through inhibiting the mitogen‐activated protein kinase (MAPK) and phosphatidylinositol‐4,5‐bisphosphate 3‐kinase (PI3K)/AKT/mammalian target of rapamycin (mTOR) signaling pathway." (PMID 33377624, 2021). "In the treatment of breast cancer, PI3K, mTOR Act kinase inhibitors are also used with increasing frequency; therefore, we compared the level of gene expression associated with the PI3K/Akt/mTOR pathway with and without mutations in breast cancer patients." (PMID 33669698, 2021). "In addition, 12-deoxyphorbol 13-palmitate in Euphorbia fischeriana Steud inhibited the Vegfr-2 signaling pathway, reduced microvessel density, inhibited VEGF, and blocked the PI3K/Akt/mTOR signaling pathway, thereby resulting in inhibition of MCF-7 breast cancer cell proliferation in mice." (PMID 33995546, 2021). "In basal-like breast cancer, a significant increase in bromodomain-containing protein 4 (BRD4), lysine-specific demethylase 5B (KDM5B), and enhancer of zeste homolog 2 (EZH2) activities was detected in tumor cell populations after treatment with MEK and PI3K/mTOR inhibitors." (PMID 33597817, 2021). "However, research has not compared breast cancer cases of high levels of p-mTOR expression with healthy controls to reveal the etiologic role of mTOR as a mechanism of obesity and breast cancer development." (PMID 34330319, 2021). "In breast cancer cells, melittin was shown to suppress the EGF-induced cell motility (EGF: epidermal growth factor) and invasion by inhibiting the PI3K/Akt/mTOR (PI3K: phosphatidylinositol-3-kinase, Akt: protein kinase B, mTOR: mammalian target of rapamycin) signalling pathway." (PMID 34067049, 2021). "Our team demonstrated, for the first time, that GABARAP inhibited EMT-related breast cancer tumor progression in a cell model, an animal model and human breast cancer tissue samples, and the mechanism may involve direct regulation of the AKT/mTOR pathway." (PMID 33591943, 2021). "Breast cancer patients possess numerous genomic aberrations, many of which converge on several pathways involved in cancer cell signal transduction, such as phosphatidylinositol 3-kinase (PI3K)/AKT/mammalian target of rapamycin (mTOR) and the extracellular signal-regulated kinase (ERK) cascades." (PMID 33861751, 2021). "mTOR inhibitors have previously been studied in ER + breast cancer, but have lacked a specific biomarker predicting response, and further study of this pathway in pnSTINGlow tumors may indicate a means of selecting patients for this therapy." (PMID 34172750, 2021). "Interestingly, in the FMCp HER2-negative cell line, good results were obtained, which could be explained by mTOR overexpression, something that has been reported in cats with HER2-negative mammary carcinomas and also breast cancer patients." (PMID 34437486, 2021).
breast cancer (continued). "Advances in the understanding of the molecular biology of ER+ breast cancer led to a revolution in this field with the development of a variety of therapeutic agents that are now being used in routine clinical care in patients with metastatic disease such as CDK4/6, PI3K, and mTOR inhibitors." (PMID 32309212, 2020). "Taken together, these data suggest that non-mitochondrial p66ShcA pools may augment breast cancer metastasis by engaging the AKT/mTOR pathway to potentiate numerous stages of the metastatic cascade." (PMID 31941526, 2020). "However, in breast cancer, the relationship between the circadian gene BMAL1 and the tumor microenvironment is still largely unknown, and it is insufficient to explain only mTOR signaling pathway." (PMID 32316196, 2020). "It is plausible that the known alternative pathways for growth, such as the epidermal growth factor receptor and PI3K/AKT/mTOR pathways, are responsible for the association between poor prognoses and high parity in luminal B-like (HER2 negative) subtype breast cancers." (PMID 32923400, 2020). "Total mTOR protein levels are elevated in breast cancer compared to normal cells." (PMID 32012648, 2020). "Deregulated lipid metabolism and enhanced FA synthesis have been described in different types of breast cancer: for example, FASN can be upregulated by HER2 signalling and induced by sterol regulatory element-binding protein 1 (SREBP1) under the control of mTOR." (PMID 32899149, 2020). "Therefore, we speculated that IGSF10 might mechanistically regulate the growth of breast cancer cells through the mTORC1 and PI3K/Akt/mTOR signaling pathways." (PMID 33150070, 2020). "Breast cancer cells lacking expression of functional BRCA1 are more sensitive to mTOR inhibitors." (PMID 31771139, 2019). "In conclusion, the molecularly matched off‐label use of everolimus might not provide sufficient benefit for refractory breast cancer patients harboring PI3K/ATK/mTOR pathway alterations." (PMID 31385461, 2019). "In MDA-MB-231 human breast cancer cells, honokiol downregulated the expression and phosphorylation of c-Src, epidermal growth factor receptor (EGFR), and Akt, and consequently led to the inactivation of mTOR and its downstream signal molecules including 4E-binding protein (4E-BP) and p70 S6 kinase." (PMID 31877856, 2019). "Indeed, the inhibition of PI3K/AKT/mTOR activity by specific inhibitors leads to a decrease in the CSC population in nasopharyngeal carcinoma, glioma pancreatic carcinoma, lung cancer, prostate cancer and breast cancer." (PMID 31366089, 2019). "Recent studies have found that frankincense essential oil can effectively inhibit the growth of breast cancer (BC) cells and induce apoptosis of BC cells by regulating AMPK/mTOR pathway." (PMID 31450584, 2019). "While much effort has been devoted to studying and targeting of well-recognized breast cancer drivers, including the estrogen receptor (ER), HER2 receptor, and the PI3K/AKT/mTOR pathways, many aspects of breast cancer biology, which could offer new treatment approaches, remain relatively unexplored." (PMID 30410118, 2018). "Since altered expression of protein kinase B (PKB)/Akt in breast cancer cells affect N-myristoyltransferase 1 (NMT1) expression and activity, we investigated whether mTOR, a downstream target of PKB/Akt, regulates NMT1 in ER positive breast cancer cells (MCF7 cells)." (PMID 30154572, 2018). "Three flavonoids (IH, GN, and Aca) induced cell cycle arrest at G2/M phase, apoptosis, and autophagy in human breast cancer cells, in which downregulation of PI3Kγ-p110 and consequent interruption of PI3K/AKT/mTOR/p70S6K/ULK signaling pathway might be closely involved." (PMID 30050147, 2018).
breast cancer (continued). "Furthermore, high CAP1 expression was associated with poor tumor characteristics and correlated with expression of genes and biological pathways within growth promoting (such as Abl, RRAGC and mTOR) and cell motility processes (e.g., Arp2/3 complex, ARSB and FN1) in breast cancer." (PMID 30524378, 2018). "Additionally, migration and invasion of HER2-amplified human breast cancer cells was diminished in the absence of Rictor, or upon pharmacological mTOR kinase inhibition." (PMID 28666462, 2017). "These mainly include the PI3K/Akt/mTOR and MAPK/ERK signal pathways, downregulating ER expression via phosphorylation of the PI3K/Akt/mTOR signal pathway and phosphorylating ER Ser118 via activation of the MAPK/ERK pathway, which correlates with the poor clinical outcomes of breast cancers." (PMID 28045951, 2017). "Out of a total of 95 breast cancer samples, 5 breast-cancer samples did not have mTOR-pathway activation, and all 5 (100%) of these had PIK3CA and PTEN mutations compared to 51/90 (57%) in the breast-cancer samples with mTOR-pathway activation (χ2p=0.0134)." (PMID 29137436, 2017). "Moreover, treatment with a chemotherapeutic drug cisplatin, results in a significant increase in breast cancer stem cells, which could be partially attributed to the activation of the PI3K/AKT/mTOR pathway." (PMID 28915623, 2017). "However, treatment with the mTOR inhibitor Afinitor® achieved favorable reductions in mTOR pathway signaling and mammary tumor growth compared with mice who only lost weight without Afinitor treatment." (PMID 28959684, 2017). "Furthermore, the combination of dovitinib and the dual PI3K/mTOR inhibitor dactolisib (BEZ235) showed strong inhibition of PI3K pathway activation in vitro and in vivo, as well as antitumor activity in FGFR-expressing breast cancer models." (PMID 28183331, 2017). "Therefore, we concluded that p-mTOR overexpression was not significantly related to the survival of breast carcinoma patients regarding disease recurrence and OS." (PMID 28114374, 2017). "Total mTOR protein level is high in some cancers, such as colorectal cancer, and it correlates positively with the tumor stage 28, but the status of total mTOR protein and its impact in breast cancer cells are not well delineated." (PMID 27748082, 2016). "However, proteasome inhibition in the breast cancer cells did not induce autophagy pathway in breast cancer cells, which had resulted in an increased level of mTOR protein in the cancer cells." (PMID 27748082, 2016). "The formation of breast cancer CSCs was accompanied with transcriptional repression of three mTOR suppressors (PKAA1, DDIT4/REDD1, and deptor) as well as upregulation of phosphorylated S6K protein levels, again signifying the activation of mTOR pathway in the acquisition of CSC-like cellular states." (PMID 27826244, 2016). "In addition, TM4SF1 overexpression is also involved in the formation of pseudopodia in cancer cells, and this facilitates the invasion and metastasis of cancer cells, and TM4SF1 has recently been reported to stimulate breast cancer cell invasion and migration through PI3K/AKT/mTOR pathway." (PMID 27153056, 2016). "Although in PTEN null breast cancers, p110β activity was induced by G protein coupled receptor (GPCR), in our models of resistance to BYL719, p110β is activated in an IGF1R/IRS-dependent manner and contributes to AKT and mTOR activation, and ultimately to resistance to p110α inhibition." (PMID 27048245, 2016). "It has been previously documented for different breast cancer cell lines that sulforapahane downregulates ER-α, EGFR and HER2 proteins as well as PI3K-Akt-mTOR signaling pathway whose overactivity may contribute to resistance of ER-positive cancers to endocrine therapy." (PMID 26014809, 2016).